KRAS (KRas proto-oncogene, GTPase)
Diseases named in the same sentence as KRAS in open-access papers (continued):
Sharing a sentence is not in itself a finding about the gene and the disease.
colorectal tumors (233 papers, 1997 to 2026). "In KRAS-mutated colorectal tumors, statins have been shown to inhibit KRAS prenylation and activate endoplasmic reticulum stress, thereby increasing tumor immunogenicity." (PMID 40438592, 2025). "Colorectal tumors with KRAS mutations were frequent in some FAP patient, and the positive rates differed among the patients." (PMID 41488735, 2025). "Beyond that, there are references to higher percentages of stable disease or progression to standard chemotherapy in patients with KRAS-mutated colorectal tumors (81% versus 62% for the KRAS wild-type group)." (PMID 40868288, 2025). "Analysis of KRAS G12D in plasma samples revealed heterozygous mutations in 54% of patients with gastric cancer and 35% of patients with colorectal tumors." (PMID 39673361, 2024). "Up to 30% of colorectal tumors are estimated to arise from the alternate carcinogenesis pathway, where KRAS or APC mutations precede the development of CIMP-low, MSI-low, or MSS tumors." (PMID 37107652, 2023). "Based on the combination of these molecular markers (MSI, CIMP, and BRAF and KRAS mutations), colorectal tumors can be classified according to three carcinogenic pathways." (PMID 37107652, 2023). "Between 30 and 50% of colorectal tumors present with mutations in the Kirsten-ras (KRAS) gene and are recognized as an early molecular event in colorectal carcinogenesis." (PMID 35057499, 2022). "We analyse a specific cohort of patients from the previously published CoSMIC study who presented with colorectal cancer and synchronous liver metastases and who had their colorectal tumour analysed for KRAS mutations." (PMID 36230756, 2022). "This study explores the association between the side of the primary colorectal tumour in patients with synchronous disease and mutations in the KRAS gene on survival." (PMID 36230756, 2022). "Right-sided colorectal tumours have a predilection for KRAS mutations and G12 mutations make up about 65% of all KRAS mutations." (PMID 36284306, 2022). "Our study showed that discordance of KRAS mutation status between primary colorectal tumor and the corresponding CRLM was observed in 15.9% of patients." (PMID 33946899, 2021). "This highly sensitive technique enabled us to detect two copies of mutated KRAS G12V, further validating the colorectal tumor origin of the isolated cells." (PMID 34638450, 2021). "KRAS mutation status was evaluated in 107 patients resected for both primary colorectal tumor and corresponding CRLM at the same institution, between 2007 and 2018." (PMID 33946899, 2021). "The incidence of KRAS discordance varied according to the time interval between the KRAS mutation analysis of the primary colorectal tumor and the mutation analysis of the corresponding CRLM." (PMID 33946899, 2021). "In colorectal tumors, the G12 KRAS mutation detected in 2 out of 15 samples, is predictive for a lack of response to the EGFR inhibitors cetuximab and panitumumab, associated to primary resistance (RI)." (PMID 33947144, 2021). "If KRAS mutation status of primary colorectal tumor is representative of corresponding colorectal liver metastases (CRLM) mutational pattern, is controversial." (PMID 33946899, 2021). "Among these 74 patients, the incidence of discordance was 13.5% (10 patients), not significantly different than that observed among the 33 patients with KRAS-mutated colorectal tumor (21.2%, 7 patients; p = 0.314)." (PMID 33946899, 2021).
colorectal tumors (continued). "Previous study reported that B-Raf protooncogene, serine/threonine kinase (BRAF), and KRAS protooncogene, GTPase (KRAS) mutations, are early molecular alterations in serrated lesions and are mutually exclusive in colorectal neoplasms." (PMID 34545326, 2021). "For these reasons, in the clinical practice, the KRAS mutation status information is generally obtained from primary colorectal tumor (surgical resection or biopsy)." (PMID 33946899, 2021). "For moderate alcohol consumption levels, as in the studies analyzed in this systematic review, there is a certain risk of developing colorectal tumors but possibly through mechanisms other than those causative of KRAS mutations." (PMID 32723394, 2020). "Findings on dietary folate or red blood cell (RBC) folate in relation to KRAS mutations in colorectal tumors were inconsistent in the studies included in the present systematic review." (PMID 32723394, 2020). "Earlier testing has the potential to identify resistance conferring mutations and direct patients away from a futile therapy such as EGFR directed therapy for KRAS mutations in colorectal tumors." (PMID 32760731, 2020). "Mutation profiles for KRAS/NRAS have previously been shown to be highly concordant between samples from the same colorectal tumor." (PMID 33014822, 2020). "Mutations were identified in 66.4% of colorectal tumors with KRAS (41.5%) and PIK3CA (14.7%) being among the most frequently mutated genes, in line with previous studies." (PMID 32087721, 2020). "KRAS is an intracellular signaling molecule, and about 40% of colorectal tumors have KRAS mutations, so identifying the key signaling pathways affected by KRAS mutations help us understand how to conduct drug-targeted therapy." (PMID 33324638, 2020). "APC and KRAS mutations co-occurred in 10/152 (6.6%) of colorectal tumours, with a tendency towards mutual exclusivity." (PMID 32087721, 2020). "Approximately 35–45% of patients with colorectal tumors have mutation in KRAS gene, while BRAF V600E mutation is found in about 5–15% of colorectal adenocarcinomas." (PMID 29127628, 2019). "Although KRAS mutations are present in 30–40 per cent of colorectal tumours with liver metastases, there are many other potential mutational combinations in CRLMs." (PMID 31388645, 2019). "Implications: This model is an excellent preclinical platform to molecularly characterize the KRAS mutated colorectal tumors and discern appropriate therapeutic strategies to improve disease management and overall survival." (PMID 31766149, 2019). "While the concordant BRAF mutation and the MSI status were observed in 100% (18 of 18) paired samples of primary colorectal tumours and corresponding ovarian metastases, the KRAS mutation concordance was observed in 83.3% (15 of 18) of them." (PMID 29662660, 2018). "In fact, current molecular phenotyping of colorectal tumors is usually linked to the traditional determination of somatic mutations in well-known oncogenes such as KRAS and BRAF." (PMID 30537927, 2018). "Stimulation of a murine KRAS-mutant colorectal tumor cell line (C26) with CD95 ligand caused an increase in colony-forming potential." (PMID 28300842, 2017). "It has been shown in several experiments that the KRAS mutations in primary colorectal tumors play a prognostic role as a predictor of resistance to the anti-EGFR antibodies." (PMID 28580315, 2017). "More than half (69.2%) had KRAS-mutated colorectal tumors with primary tumors of the right colon comprising 42.3% of the population." (PMID 29108355, 2017). "In the present study we investigated the association of mRNA expression levels of TRAIL receptors (DR4 and DR5) and selected IAP genes with the presence of KRAS mutations in colorectal tumors." (PMID 27827395, 2016).
colorectal tumors (continued). "Here, cIAP1 and cIAP2 were found significantly down-regulated in CRC, and low expression of cIAP2 was significantly correlated with detection of KRAS mutations in the colorectal tumors under study." (PMID 27827395, 2016). "We therefore assessed each of the six candidate KRAS SLs identified in the LIM1215 screen in a second KRAS isogenic system consisting of a second colorectal tumour cell model, SW48, in which KRAS mutant alleles were also introduced by AAV gene targeting." (PMID 26881434, 2016). "KRAS is mutated in about 20-25% of all human cancers and especially in pancreatic, lung and colorectal tumors." (PMID 26028667, 2015). "Although sometimes grouped with serrated pathway cancers, colorectal tumors that are KRAS-mutated, CIMP-low, and MSS have been suggested to arise from an ‘alternative pathway’." (PMID 26337942, 2015). "KRAS mutations were encountered in 40% of appendiceal vs. 30% colorectal tumors, while BRAF mutations were seen in 40% of colorectal PM and none of the patients with appendiceal PM (p = 0.06)." (PMID 25593974, 2014). "KRAS: Initially, KRAS mutations have been observed in colorectal tumours independently of their MSI status." (PMID 25361007, 2014). "CNA of the KRAS locus occur independently of the KRAS mutation status in a considerable percentage of colorectal tumours (21.2%) as assessed in a large and unselected mCRC population." (PMID 22804917, 2012). "Previous work in zebrafish has shown that activated KRAS enhances Wnt signaling in Apc-deficient zebrafish larvae and human colorectal tumors." (PMID 22973180, 2012). "This study has analyzed in detail the role of BRAF/ KRAS/ PIK3CA mutation status of particular colorectal tumours on predicting efficient therapeutic treatments with the BRAF and the PI3K inhibitors as well as their rational combination with TRAIL." (PMID 21738740, 2011). "We observed a concordant KRAS mutation status in 96.4% of 305 paired samples of colorectal tumours and liver metastases." (PMID 21364579, 2011). "KRAS mutations occur in approximately 38% of colorectal tumours and involve codon 12 and 13 in >96% of cases." (PMID 21364579, 2011). "KRAS mutations occur relatively early in colorectal tumor progression, and therefore they are usually present in the majority of the transformed cells within a KRAS mutant tumor." (PMID 22216189, 2011). "An additional explanation for the suboptimal response rates to anti-EGFR antibodies in patients with KRAS wild-type tumours is discordance of KRAS mutation status between primary colorectal tumours and corresponding metastases." (PMID 21364579, 2011). "We analysed KRAS codon 12 and 13 mutations in 320 matched primary colorectal tumours and liver metastases." (PMID 21364579, 2011). "Current data on the concordance in KRAS mutation status between primary colorectal tumours and metastases are conflicting." (PMID 21364579, 2011). "We assessed the concordance of KRAS mutation status in a study of 305 primary colorectal tumours and their corresponding liver metastases." (PMID 21364579, 2011). "We observed a high concordance of KRAS mutation status of 96.4% (95% CI 93.6–98.2%) between primary colorectal tumours and their corresponding liver metastases." (PMID 21364579, 2011). "Colorectal tumours frequently harbour activating mutations in the KRAS proto-oncogene, which drives tumour progression." (PMID 20354524, 2010). "Kobunai and colleagues detected KRAS mutations in an additional 25 out of 224 colorectal tumors when a highly sensitive PNA-clamping method was compared to direct sequencing." (PMID 21110880, 2010). "For NSCLC, we detected in 15/41 (36.6%) KRAS-mutated cancer tissue samples, in 6/20 (30%) KRAS mutations in colorectal specimens, in 14/19 (73.7%) pancreatic tumor samples, and in 9/20 (45%) colorectal tumor samples from the interlaboratory comparison." (PMID 21197450, 2010).
colorectal tumors (continued). "Our results suggest a role for KRAS mutations in the propensity of primary colorectal tumors to metastasize to the lung." (PMID 20020061, 2009). "Recent data suggests that both cetuximab and panitumumab are effective only in the treatment of colorectal tumors with a wild-type KRAS gene; patients with tumors harboring mutations in KRAS are resistant to the two EGFR inhibitors." (PMID 19678929, 2009). "The incidence of KRAS mutations in colorectal tumors ranges from 35% to 45%, and KRAS mutations seem to occur early in carcinogenesis." (PMID 20020061, 2009). "As far as we know, this is the first study to analyse primary colorectal tumors and their related lung metastases and correlated KRAS mutational status based on both clinicopathological features and survival data." (PMID 20020061, 2009). "It has been reported that colorectal tumors with KRAS mutations also show DNA hypermethylation at CIMP-associated markers, albeit at a low frequency, and have high levels of DNA methylation of genes that undergo age-associated DNA hypermethylation." (PMID 20027224, 2009). "Future research should also further validate the diagnostic efficacy of FC across different ethnic populations, clarify its relationship with colorectal tumors staging and localization, and explore its association with tumor molecular characteristics (such as KRAS mutations, BRAF mutations)." (PMID 40703287, 2025). "This could be correlated with its lower prevalence distribution in colorectal tumors, possibly due to clones harboring mutations in codon 12 being more prone to the development of KRAS-driven cancer, thus leading to their broader distribution." (PMID 39001385, 2024). "Four hundred fourteen colorectal tumors were screened for KRAS and NRAS mutations." (PMID 37277698, 2023). "As our current study suggests, KRAS‐mutated colorectal neoplasms may also be resistant to the beneficial effects of hPDI." (PMID 35998061, 2022). "It is well studied that KRAS mutations were present in a majority of colorectal tumors." (PMID 36439454, 2022). "Clearly, the LIM1899 cell line is dependent on the EGFR signalling pathway for proliferation in vitro; this result is rather unexpected given that these cells harbour a KRAS mutation, which, in the majority of colorectal tumours, circumvents the EGF signalling pathway inhibition in the clinic." (PMID 35301819, 2022). "The discordance of KRAS mutation status between the primary colorectal tumor and the corresponding CRLM may represent a possible explanation for the resistance to monoclonal antibodies targeted therapies." (PMID 33946899, 2021). "In this situation, it is clear that the only evaluation of KRAS mutation status in primary colorectal tumor may be inadequate to predict response to anti-EGFR therapy of the corresponding CRLM and may provide limited information prior to multimodal treatment." (PMID 33946899, 2021). "Understanding how KRAS mutations arise in colorectal tumors may provide valuable clues for prevention strategies." (PMID 32723394, 2020). "Moreover, LRP6 is hyperphosphorylated in KRAS-mutated cells and in patient-derived colorectal tumours." (PMID 31412666, 2019). "By incubating murine NIH-3 T3 cells with plasma from patients with KRAS mutated colorectal tumors followed by injection into mice, the development of tumors could subsequently be observed as well as the detection of human KRAS mutations in the mice’ plasma." (PMID 30364656, 2018). "Testing for NRAS mutations is now a standard of care in KRAS wild-type colorectal tumors." (PMID 29682098, 2018). "Approximately 30-50% of colorectal tumors are known to have a mutated KRAS gene." (PMID 28460460, 2017).
colorectal tumors (continued). "Therefore, the addition of PBR extract to cetuximab suppressed KRAS-mutated colorectal tumor growth invivo." (PMID 28800074, 2017). "Up to 60% of colorectal tumors exhibit gain-of-function mutations in KRAS, NRAS and BRAF genes." (PMID 27582544, 2016). "Since oncogenic mutations in KRAS are predominantly found in human lung, pancreatic and colorectal tumors, it would be intriguing to assess whether KRAS4A and 4B would display a differential carcinogenic potential in those tissues as well." (PMID 26799184, 2016). "Having established that multiple independent CDK1 siRNA duplexes caused CDK1 silencing and KRAS selectivity, we assessed cell growth inhibition in a panel of 20 genetically diverse colorectal tumour cell line models transfected with multiple different CDK1 siRNAs." (PMID 26881434, 2016). "However, the observed prevalence of KRAS mutation is still lower than the figures reported in other studies and fits to the known rate of KRAS mutation in primary colorectal tumors." (PMID 26715198, 2016). "Approximately 35-40% of colorectal tumors exhibit mutations in KRAS gene." (PMID 27582544, 2016). "However, activating mutations in BRAF and KRAS only occur in approximately 5-15% and 30-45% of colorectal tumours, respectively." (PMID 27248823, 2016). "However, it has been shown previously that there is a high concordance of KRAS exon 2 mutation status between primary colorectal tumours and their corresponding liver metastases." (PMID 27784278, 2016). "Mutations in KRAS are evident in 30–40% of colorectal tumors." (PMID 26426996, 2015). "Interestingly, colorectal tumors that developed due to chronic ulcerative colitis had a lower frequency of KRAS mutation." (PMID 26104296, 2015). "The reason for increased incidence of lung metastases in KRAS mutated colorectal tumors remains unknown at this moment." (PMID 25888291, 2015). "Some colorectal tumours have both KRAS and PI3K pathway mutations." (PMID 25361007, 2014). "Only 3 and 2 depressed colorectal neoplasms had mutations in KRAS and BRAF respectively." (PMID 25551625, 2014). "Specifically, KRAS mutations at codon 12 could be correlated to reduced apoptosis in vitro and lower apoptotic indices in colorectal tumors." (PMID 25198428, 2014). "CXCL8 signaling is also known to be promoted downstream of KRas mutations, suggesting that enrichment of lung, pancreatic or colorectal tumors harboring KRas mutations may be more responsive to anti-CXCL8 therapeutics." (PMID 24276377, 2013). "In addition, few studies have observed the coexistence of more than one mutation in the KRAS gene within the same colorectal tumor, correlating this type of alteration with clinical and morphological features." (PMID 23761841, 2013). "However, among six BM from colorectal tumors, we identified KRAS mutations in three cases and BRAF mutations in two other cases." (PMID 23930206, 2013). "KRAS hotspot somatic mutations were seen in 21 of the 54 colorectal tumors (∼39%)." (PMID 23505554, 2013). "KRAS gene mutations play an important role in the carcinogenesis of colorectal tumors." (PMID 29147353, 2013). "KRAS oncogenic mutations occur in approximately 40% of colorectal tumors." (PMID 29147353, 2013). "Profiling colorectal tumours for wild type versus mutated KRAS gene has been valuable for selecting patients who are unlikely to benefit with cetuximab or panitumumab; however, these KRAS mutations are uncommon in HNSCC." (PMID 22745668, 2012). "In contrast, KRAS mutations were only associated to with low levels of methylation as it was previously observed in primary colorectal tumours, demonstrating that KRAS mutations are associated to mild effects in the methylation profile during colorectal carcinogenesis." (PMID 18782444, 2008). "However, KRAS mutations are common in colorectal tumors, as a result of which the same mutation may be found in all multiple and recurrent tumors." (PMID 39325309, 2024).